SIRT6 (sirtuin 6)
Diseases named in the same sentence as SIRT6 in open-access papers (continued):
Sharing a sentence is not in itself a finding about the gene and the disease.
breast cancer (continued). "Therefore, our results provide evidence that SIRT6-OE is a marker of poor prognosis in HER2-positive breast cancer and that SIRT6 inhibition might be beneficial in this cancer type." (PMID 38081972, 2023). "However, in the same tumor type, SIRT6 may also play dual roles in tumor progression by activating different signaling pathways, such as breast cancer and HCC." (PMID 35172823, 2022). "However, downregulated SIRT6 favored better DFS in patients with breast cancer (P < 0.05)." (PMID 35172823, 2022). "Moreover, SIRT6 can promote paclitaxel and epirubicin resistance in breast cancer." (PMID 32372224, 2020). "Notwithstanding, recent studies have supported the breast cancer-promoting effects of SIRT1 and SIRT6." (PMID 40214422, 2025). "AKT1-mediated phosphorylation promotes MDM2-dependent ubiquitination and degradation of SIRT6, thereby contributing to trastuzumab resistance in HER2-positive breast cancer." (PMID 41463311, 2025). "Given the dual roles of both SIRT1 and SIRT6 in breast cancer, functional studies involving the introduction of EVs expressing SIRT1 and SIRT6 to breast cancer cells are required to determine the definitive roles of both enzymes in breast cancer." (PMID 40214422, 2025). "In our recent review, we discussed the dual roles of both SIRT1 and SIRT6 in breast cancer, highlighting the tumor-suppressing and tumor-promoting effects of SIRT1 and SIRT6 in breast cancer." (PMID 40214422, 2025). "Sirtuin 6 (SIRT6) is a kind of NAD+-dependent III deacetylase, and it can regulate the occurrence of cancer, including liver and breast cancers, by regulating a variety of cellular signal pathways." (PMID 36874003, 2023). "As shown for SIRT6-OE, TBX3 low expression is predictive of poor prognosis specifically in HER2-positive breast cancer patients." (PMID 38081972, 2023). "Here, we investigate the impact of SIRT6-overexpression (SIRT6-OE) in Delta16HER2 mice, which are a bona fide model of HER2-positive breast cancer." (PMID 38081972, 2023). "In this regard, even if the expression of TBX3 and SIRT6 is inversely correlated in both basal-like and HER2-positive breast cancer patients, their paired expression levels have opposite predictive meanings in these two cancer subtypes." (PMID 38081972, 2023). "Icariin induces breast cancer cell apoptosis through the PI3K/AKT and SIRT6/NF-κB signalling pathways." (PMID 36678509, 2022). "In breast cancer, SIRT6 can enhance the expression and activity of pyruvate dehydrogenase (PDH), thereby enhancing oxidative phosphorylation in breast cancer cells and promoting the occurrence of breast tumors in mice." (PMID 35463332, 2022). "SIRT6 role in cancer is reminiscent of other sirtuins such as SIRT2, which has been shown to act as either tumor suppressor or promoter in breast cancer, depending on tumor grade." (PMID 33800266, 2021). "In breast cancer cells, CSNK2A1 phosphorylates SIRT6 on Ser338, and this process stimulates cell proliferation through the regulation of β-catenin and NFκB." (PMID 34359939, 2021). "Although the authors further demonstrated that SIRT6 overexpression protects Delta16HER2 breast tumor cells against oxidative DNA damage, the contributions of the enzyme to specific breast cancer cell survival mechanisms were not investigated." (PMID 40214422, 2025). "Similar functional effects of Apigenin were observed by using an additional human breast cancer cell model (MDA-MB-468, TNBC, highly metastatic) whose stemness features were abolished by the inhibition of sirtuin-3 (SIRT3) and sirtuin-6 (SIRT6) protein levels, as supported by in silico analyses." (PMID 38791608, 2024). "KMP inhibits SIRT3 and SIRT6 in TNBC, thereby promoting breast cancer progression." (PMID 39479446, 2024). "Indeed, if on the one hand the concomitant high SIRT6 and low TBX3 expression predicts better prognosis in basal-like breast cancer, on the other, it is indicative of poor prognosis in HER2-positive breast cancer patients." (PMID 38081972, 2023).
breast cancer (continued). "Moreover, NAMPT is a direct substrate of SIRT6 deacetylation, increasing NAMPT enzymatic activity in breast cancer 10.1096/fj.201800321R." (PMID 37491379, 2023). "Indeed, high SIRT6 expression correlates with a worse prognosis in both ER + and ER- HER2-enriched breast cancer cases." (PMID 38081972, 2023). "However, data from cBioPortal, GOBO and bc-GenExMiner confirmed that SIRT6-OE is indeed predictive of good and poor prognosis in basal-like and HER2-positive breast cancer patients, respectively." (PMID 38081972, 2023). "Our findings indicated SIRT6 as an oncogene, which was not consistent with its function in breast cancer and lung cancer." (PMID 35251169, 2022). "Here, we obtained the novel findings that SIRT6 is involved in the modulation of breast cancer cell invasion and migration by regulating MMP-9 expression in breast cancer cells, suggesting that SIRT6 is a novel target molecule for the prevention of breast cancer." (PMID 35840633, 2022). "However, another study showed that ectopic expression of SIRT6 reduced pAkt, hexokinase-2, and PDH kinase-1 protein levels, thereby inhibiting metabolic pathways in breast cancer." (PMID 35463332, 2022). "Our in vivo data, showing delayed mammary tumor development and increased survival in MMTV-PyMT+/−; Sirt6+/− mice as compared to MMTV-PyMT+/−; Sirt6+/+ animals, are in line with the previously reported adverse prognostic significance of high SIRT6 expression in BC." (PMID 33482921, 2021). "Prolong treatment of breast cancer cells with AKT inhibitors (which inhibit AKT phosphorylation) induces dephosphorylation of FOXO3a, nuclear translocation, and destruction of its binding to SIRT6, resulting in FOXO3a acetylation and BRD4 recognition." (PMID 34679680, 2021). "In this regard, SIRT6 mediates breast cancer cell cancer survival and oxidative stress resistance by regulating intracellular NAMPT activity and NAD(P)(H) levels, suggesting the use of SIRT6 inhibitors and agents inducing oxidative stress as a promising strategy for cancer treatment." (PMID 32488123, 2020). "SIRT6 also represses FOXO3 acetylation to promote clonal renewal and survival in breast cancer." (PMID 32372224, 2020). "The biological role of SIRT6 in HCC chemosensitivity is consistent with previous studies that SIRT6 depletion or inhibitor enhanced chemosensitivity in prostate cancer and breast cancer, respectively." (PMID 29563873, 2018). "SIRT6 increased resistance to paclitaxel and epirubicin in MCF7 breast cancer cells." (PMID 30524965, 2018). "CK2 could act through several signaling pathways and mechanisms in breast cancer such as NF-κB, JAK/STAT, MAPK, Akt/MTOR, SIRT6, and miRNA expression." (PMID 28134850, 2017). "It has been reported that SIRT6 confers paclitaxel and epirubicin resistance in MCF-7 cells, which has suggested that SIRT6 is a potential marker and therapeutic target for paclitaxel- and epirubicin-resistant breast cancer." (PMID 24386592, 2013). "Moreover, SIRT6 promoted breast cancer metastasis by upregulating matrix metalloproteinase-9 (MMP-9) through the MAPK, NF-κB, and AP-1 pathways; silencing SIRT6 reduced cell invasion and migration in MCF-7 and MDA-MB-231 cells, suggesting its direct role in metastatic progression." (PMID 41471349, 2025). "Also, in breast cancer, there is an overexpression of SIRT1 and SIRT6." (PMID 40214422, 2025). "There was no significantly correlation between SIRT6 expression and OS observed in breast cancer." (PMID 35172823, 2022). "Thus, since the typical tumor latency in MMTV-PyMT 129 mice is between 10 and 12 weeks, the use of Sirt6−/− mice would not have allowed us to assess the effect of Sirt6 depletion on mammary tumor development." (PMID 33482921, 2021).
breast cancer (continued). "Some studies have shown that long non-coding RNA NONHSAT101069, SIRT6 protein, transforming growth factor (TGF-β), fibroblast growth factor receptor (FGFR) 4 rs1966265 and FGFR2 rs2981578 get involved in anthracycline resistance in breast cancer, as well as other factors." (PMID 33102228, 2020). "Lower levels of EP300 and higher levels of the nuclear deacetylases, sirtuins (e.g., SIRT1 and SIRT6) were also detected in the BT474-LapR cells, which might also contribute to the reduced FOXO3 activity in BT474-LapR cells and therefore lapatinib resistance in HER2-positive breast cancer cells." (PMID 31357743, 2019). "Unlike in other types of cancer, including breast cancer, SIRT6 is overexpressed in prostate tumor tissues and cells (PC3, DU145, 22RV1, and LNCaP), with high SIRT6 expression correlating with poor overall survival of prostate cancer patients." (PMID 36291902, 2022). "As opposed to these studies, in mammary tumors from MMTV-PyMT+/−; Sirt6+/− mice and in MDA-MB-231 cells with silenced SIRT6, we did not detect increased PDK1 or PDK4 expression." (PMID 33482921, 2021). "While the biochemical role of SIRT6 in breast cancer is still not completely established, this study came to conclusion that stabilizing SIRT6 may be a clinical strategy to overcome trastuzumab resistance in breast cancer patients, therefore increasing their survival prognostics." (PMID 31591350, 2019). "Interestingly, cytoplasmic FOXO3 was found to be positively correlated with the expression levels of SIRT6 (p < 0.001) but not SIRT1 in HER2+ (ER+ and ER−) breast cancer patients." (PMID 31357743, 2019).
hepatocellular carcinoma (53 papers, 2014 to 2026). A malignant tumor that arises from hepatocytes. "SIRT6 has been reported to decrease E-cadherin (encoded by the CDH1 gene) in normal or hepatocellular carcinoma cell lines through the deacetylation of Beclin 1, a key regulator of autophagy, and the promotion of autophagy-mediated E-cadherin degradation." (PMID 36831330, 2023). "Similarly, USP48, primarily localized to the nucleus, impedes metabolic reprogramming to inhibit hepatocellular carcinoma development by removing K48-linked ubiquitination at the K33 and K128 sites of SIRT6 to stabilize SIRT6." (PMID 38245760, 2024). "Sirt6 is widely associated with in a variety of disease including ischemia/reperfusion and alcoholic hepatic injury, cardiovascular disease, kidney disease and hepatocellular carcinoma." (PMID 32206298, 2020). "Similarly, loss of SIRT6 could induce global hypomethylation, hypoglycemia, and increased fat deposition in hepatocellular carcinoma." (PMID 30987683, 2019). "On the other hand, however, the increased lifespan associated with SIRT6 could imply that SIRT6 may promote tumor formation and, in fact, recently an increase of SIRT6 has been associated with enhancement of tumorigenicity of hepatocellular carcinoma cells in the presence of TGF-β1, H2O2, and HOCl." (PMID 26798421, 2016). "Investigation of hepatocellular carcinoma demonstrated that SIRT6 suppressed the NF‐κB activation, and markedly impaired the initiation and development of cancer cells." (PMID 37936548, 2024). "Alternatively, Duet al. determined that METTL14 regulates SIRT6 in hepatoma cells by regulating m6A levels onUSP48 (ubiquitin-specific peptidase 48) mRNA; in another study, it was shown that SIRT6 protects smooth muscle cells from senescence and reduces AS." (PMID 37394885, 2023). "This is because the ubiquitin-specific peptidase 48 (USP48) in hepatoma cells can combine with SIRT6, a histone deacetylase, to improve the stability of SIRT6, which plays a role in weakening the glycolysis of hepatoma cells." (PMID 37582735, 2023). "SIRT6 has also been shown to promote hepatocellular carcinoma growth through the inhibition of cell senescence and cell growth arrest." (PMID 36831330, 2023). "Downregulation of SIRT6 leads to an increase in doxorubicin-induced death of hepatocellular carcinoma cells by inducing FOXO3 to translocate into the nucleus and bind its target genes P27 and Bim." (PMID 35915188, 2022). "ANXA2 acted an as an oncogene in hepatocellular carcinoma progression, which was modified by SIRT6/UBE3A." (PMID 35977942, 2022). "In liver cancer, upregulation of SIRT6 is very common in liver cancer tissues and is highly correlated with poor overall survival rate, disease-free survival, hepatocellular carcinoma (HCC) cell migration, tumor size, tumor grade, and vascular invasion." (PMID 35463332, 2022). "It is only recently that UBCS039 and MDL-800 were reported to activate SIRT6 and decrease proliferation of lung, hepatocellular carcinoma, and pancreatic cancer cells." (PMID 34650436, 2021). "In hepatocellular carcinoma tissues reduced levels of SIRT6 were observed, along with high levels of acetylated PKM2 at residue K433." (PMID 33800266, 2021). "In the hepatocellular carcinoma cells SIRT6 overexpression has been reported to arrest cell cycle in the G1-phase which subsequently promote tumor suppressing effect in liver." (PMID 33684691, 2021). "Bhardwaj and Das indicated that the ectopic expression of SIRT6 inhibited the migratory and invasive ability of hepatoma HepG2 cells in vitro." (PMID 33335996, 2020). "Sirt6 suppression in both human prostate cancer and hepatocellular carcinoma had further underscored its ability to sensitize tumors to chemotherapy and induce apoptosis." (PMID 32711549, 2020). "The expression of SIRT6 is down-regulated in colon cancer, hepatocellular carcinoma, and head and neck squamous cell carcinoma." (PMID 31128573, 2019).
hepatocellular carcinoma (continued). "In hepatocellular carcinomas, SIRT6 increased sensitivity to chemotherapeutic agent-mediated apoptosis of HepG2 cells." (PMID 30524965, 2018). "Taken together, these results indicated SIRT6 depletion enhanced chemosensitivity of human hepatoma cells by downregulating MDR1 expression through suppressing C/EBPβ." (PMID 29563873, 2018). "Depletion of SIRT6 sensitized pancreatic cancer cells to gemcitabine, and hepatocellular carcinoma cells to chemotherapeutic agents via downregulation of MDR1 expression." (PMID 30524965, 2018). "The previous studies demonstrated that OA induced autophagy in colon cancer cells by regulating the p38/FOXO3a/Sirt6 pathway, and in hepatoma cells through the Akt/mTOR pathway, reflected in the decreased p62 expression and increased LC3-II and Beclin-1 expression." (PMID 40969279, 2025). "It was shown that SIRT6 functions as a tumor suppressor in hepatocellular carcinoma (HCC) through the binding and deacetylating of nuclear pyruvate kinase M2 (PKM2), which suppresses the oncogenic functions of PKM2, resulting in decreased cancer cell proliferation, migration, and invasiveness." (PMID 38203666, 2023). "In another report, SIRT6 has been shown to mediate the tumor-promoting effect of NAD(P)H:quinone oxidoreductase 1 (NQO1) on hepatocellular carcinoma through the activation of AKT serine/threonine kinases in PLC/PRF/5 and Huh7 cell lines and an orthotopic tumor cell implantation mouse model." (PMID 36831330, 2023). "Similarly, the proliferation and cloning effects of hepatocellular carcinoma cells were weakened after SIRT6 was knocked out." (PMID 34927546, 2021). "It has been shown that SIRT6 overexpression favors hepatoma cell proliferation through the extracellular signal-regulated kinases 1/2 (ERK1/2) pathway, whereas SIRT2 plays a critical role in promoting HCC metastasis and invasion rather than cell growth by re-routing liver cancer metabolism." (PMID 33920670, 2021). "SIRT6 expression was abnormal in various gastrointestinal tumor tissues, including colorectal cancer, gastric cancer (GC), pancreatic cancer, and hepatocellular carcinoma (HCC)." (PMID 33335996, 2020). "Thus, we identified the specific role of SIRT6 in the progression of hepatocellular carcinoma (HCC)." (PMID 27824900, 2016). "As a result, SIRT6 suppresses hepatocellular carcinoma (HCC) growth through the inhibition of glycolysis." (PMID 36831330, 2023). "In patients with hepatocellular carcinoma, miR-122 and SIRT6 negatively regulate each other and miR-122 over-expression or down-regulation leads to a decrease or induction of SIRT6 protein levels, respectively, and the SIRT6-miR-122 correlation may serve as a biomarker for liver cancer prognosis." (PMID 35743814, 2022). "SIRT6 deacetylates Beclin-1 in hepatocellular carcinoma (HCC) cells and stimulates the autophagic degradation of E-cadherin, which in turn promotes epithelial-mesenchymal transition (EMT) in HCC cells and ultimately increases metastasis in liver cancer." (PMID 35915188, 2022). "This correlation has been discovered in hepatocellular carcinoma (HCC), whereby c-Fos-mediated SIRT6 transcriptional activation initiates a tumor-suppressor pathway that will be explained in detail in the following section." (PMID 33800266, 2021). "SIRT6 expression was downregulated in human hepatocellular carcinoma (HCC) cells and tissue compared to adjacent normal tissue." (PMID 31591350, 2019). "Recently, a number of studies have identified SIRT6 as a key regulator of hepatocellular carcinoma (HCC), but the functional roles of SIRT6 in liver cancer are inconsistent." (PMID 29100306, 2017). "In contrast, SIRT6 is downregulated in pancreatic cancer, head and neck squamous cell carcinomas, human hepatocellular carcinoma (HCC) and colorectal carcinoma." (PMID 27777384, 2016). "Additional writers and readers, such as METTL14 in hepatocellular carcinoma (HCC), stabilize oncogenic transcripts like SIRT6." (PMID 40761481, 2025).
hepatocellular carcinoma (continued). "In hepatocellular carcinoma (HCC) cells, the overexpression of SIRT6 impairs cancer cell proliferation via the inhibition of ERK1/2 signaling and induces apoptosis by increasing cleaved caspase-3 levels." (PMID 38203666, 2023). "Here, we report that in hepatocellular carcinoma (HCC) cells under glucose-deprived conditions, SCIC2.1 treatment induced overexpression of SIRT1, SIRT3, and SIRT6, modulating metabolic response." (PMID 37715252, 2023). "Previous studies showed that knockdown of SIRT6 can inhibit MAPK/ERK and PI3K/AKT/mTOR signaling pathways in hepatocellular carcinoma and diffuse large B-cell lymphoma." (PMID 37542062, 2023). "In hepatocellular carcinoma (HCC), SIRT6 can potentiate apoptosis resistance by repressing the transcription of the pro-apoptotic gene Bax." (PMID 34225779, 2021). "In BEL7405 hepatocellular carcinoma cells, MDL-800 decreased the acetylation level of H3K9 and H3K56, which are known SIRT6 deacetylation targets." (PMID 34650436, 2021). "Further evidence suggests the tumor suppressor role of SIRT6 in other types of cancer such as hepatocellular carcinoma (HCC), lung cancer and nasopharyngeal carcinoma (NPC), where SIRT6 has been found downregulated at gene level compared to normal tissues." (PMID 33800266, 2021). "MDL-800 is a SIRT6 activator that induced global decrease in the acetylation of both H3K56 and H3K9 in human hepatocellular carcinoma and was effective in tumor xenograft model." (PMID 32587297, 2020). "SIRT6 promotes cell apoptosis by modulating the PTEN/AKT and ERK1/2 signaling pathways in colorectal and hepatocellular cancers." (PMID 31817470, 2019). "The only published report on SIRT6 regulation to date came from studies with a mouse hepatoma cell line, Hepa1-6, which showed that a complex of SIRT1, FOXO3a and NRF1 up-regulated SIRT6 upon nutritional stress." (PMID 25816777, 2015). "In the Cancer Genome Atlas (TCGA) datasets, hepatocellular carcinoma patients who did not have a negative correlation between SIRT6 and miR-122 expression had a better prognosis than those who had a negative correlation." (PMID 36831330, 2023). "Notably, MDL-800 decreased acetylation of the Sirt6 substrates histone H3K9 and H3K56 in human hepatocellular carcinoma (HCC) and non-small cell lung cancer (NSCLC) cell lines in a concentration-dependent manner and induced Sirt6-mediated G0–G1 phase cell cycle arrest." (PMID 38474697, 2024).